MUC6 (mucin 6, oligomeric mucus/gel-forming (gene/pseudogene))
Diseases named in the same sentence as MUC6 in open-access papers (continued):
Sharing a sentence is not in itself a finding about the gene and the disease.
colorectal polyps (1 paper, 2010). "MUC5AC and MUC6, which are gastric mucins, are believed to express de novo in certain colorectal polyps." (PMID 20929551, 2010). "For instance, there is a large body of controversy regarding the alterations of MUC5AC and MUC6 in colorectal polyps." (PMID 20929551, 2010). "MUC1, MUC2, MUC5AC, and MUC6 have the potential to be used as predictors of malignant transformation and invasion to mucosa or the muscularis mucosae in colorectal polyps." (PMID 20929551, 2010). "The aim of the present study was to determine the pattern of expression of MUC1, MUC2, MUC5AC and MUC6 in colorectal polyps and to evaluate the applicability of using mucin expression in predicting the extent of malignant transformation in colorectal polyps." (PMID 20929551, 2010). "Binary logistic regression analysis indicated that positive staining for MUC1, and MUC6, and negative staining for MUC2 would increase the risk of invasion to mucosa or the muscularis mucosae in colorectal polyps." (PMID 20929551, 2010).
colorectal tumors (1 paper, 2019). "Although MUC6 expression was rarely observed in colorectal tumors, when it was present, the patients had a very good prognosis." (PMID 31091244, 2019).
COVID-19 (1 paper, 2021). A disease caused by infection with severe acute respiratory syndrome coronavirus 2. "It is interesting to note that MUC21 mRNA expression was only selected as a variable associated with COVID-19 severity, whereas MUC13, MUC4, and MUC6 mRNA expression were uniquely identified as variables indicative for COVID-19 presentation." (PMID 34448730, 2021). "By using the same approach, we also showed that age and mRNA expression of MUC1, MUC2, MUC4, MUC6, MUC13, MUC16, and MUC20 were the most accurate variables associated with the presence of COVID-19 among symptomatic patients (AUCROC = 91.8%; sensitivity: 90.6%; specificity: 93.3%)." (PMID 34448730, 2021).
depression (1 paper, 2024). "Given the vital role of neurotrophins in demyelinating pathologies, MUC6 may be involved in depression-related changes in the structural connectivity of white matter tracts through its involvement in neurotrophin signaling and demyelination pathways." (PMID 38461185, 2024).
dermatofibrosarcoma protuberans (1 paper, 2024). Dermatofibrosarcoma protuberans (DFSP) is a rare infiltrating soft tissue sarcoma, generally of low grade malignancy, arising from the dermis of the skin and characteristically associated with a specific chromosomal translocation t(17;22). "Mutually exclusive mutations in MUC4 and MUC6 have been identified in dermatofibrosarcoma protuberans." (PMID 39338204, 2024).
duodenal cancer (1 paper, 2025). "Our case showed MUC5AC and MUC6 staining in the duodenal cancer." (PMID 41098299, 2025).
emphysema (1 paper, 2014). "Among COPD subjects with ≥10% emphysema, chromosome 11p15.5, which includes genes AP2A2, MUC6 and CHID1, was the most significant region (rs7483870, β = 0.16L, P = 3.93 × 10−7; rs4076950, β = 0.13L, P = 2.88 × 10−6; rs4963123, β = 0.13L, P =3.40 × 10−6)." (PMID 25134640, 2014).
food allergies (1 paper, 2017). "Eighty-six variations were found in MUC6 splicing and coding regions in the three patients with RES and food allergies." (PMID 28420126, 2017).
gallbladder adenocarcinoma (1 paper, 2021). A carcinoma that arises from glandular epithelial cells of the gall bladder. "Altogether, our results showed that the tumor expression patterns of MUC6, CK17, CD10, and villin constitute candidate markers with potential prognostic value for patients with primary adenocarcinoma of the gallbladder." (PMID 33494186, 2021).
gastric papillary adenocarcinoma (1 paper, 2024). A variant of gastric adenocarcinoma with exophytic growth and elongated finger-like processes lined by cylindrical or cuboidal cells supported by fibrovascular connective tissue cores. "Clinically, gastric papillary adenocarcinoma typically overexpresses the gastric phenotype mucins MUC5AC and MUC6, which may aid in distinguishing between EGDTA and EGPA." (PMID 39540152, 2024).
glioma (1 paper, 2019). A benign or malignant brain and spinal cord tumor that arises from glial cells (astrocytes, oligodendrocytes, ependymal cells). "Consider for example, the 2-hit combination of mutations in IDH1 and MUC6 in brain lower grade glioma (LGG) tumor samples." (PMID 30700767, 2019).
Hepatitis (1 paper, 2022). Inflammation of the liver. "In conclusion, our findings suggest that genetic variations in MUC6 may help to predict cancer susceptibility and hepatitis in HCC." (PMID 36118520, 2022).
hepatoid adenocarcinoma (1 paper, 2009). An adenocarcinoma with morphologic characteristics similar to hepatocellular carcinoma, arising from an anatomic site other than the liver. "Four phenotypic categories according to the inmunohistochemical results for CD10, MUC2, MUC5AC, and MUC6 were described for both components, tubular adenocarcinomatous and hepatoid, of hepatoid adenocarcinoma." (PMID 19674468, 2009). "In contrast, no gastric phenotype (MUC5AC+, MUC6+, MUC2-, CD10-) was observed in any of the hepatoid adenocarcinoma components." (PMID 19674468, 2009).
Kidney Chromophobe (1 paper, 2022). "Then, we explored The Cancer Genome Atlas (TCGA) database and found that MUC6 mutations also occur in TCGA KICH (Kidney Chromophobe), KIRC (Kidney renal clear cell carcinoma) and KIRP (Kidney renal papillary cell carcinoma) datasets." (PMID 35574418, 2022).
kidney tumor (1 paper, 2022). "The expression data from these sets showed a robust reduction of MUC6 in kidney tumor tissues compared to control tissues." (PMID 35574418, 2022).
language disorder (1 paper, 2024). A category of disorders characterized by an impairment in the development of an individual's language capabilities, which is in contrast to his/her non-verbal intellect. "The genes SEMA6D, AUT2 and ROBO1, OXR1 and MUC6 were reported as interesting candidate genes because potential pathogenic variants co-segregated with the language disorder in affected relatives of the respective probands." (PMID 38298611, 2024).
Lynch syndrome (1 paper, 2017). An autosomal dominant hereditary neoplastic syndrome characterized by the development of colorectal carcinoma and a high risk of developing endometrial carcinoma, gastric carcinoma, ovarian carcinoma, renal pelvis carcinoma, and small intestinal carcinoma. "Our study on the secreted gel-forming mucins (MUC2, MUC5AC, and MUC6) demonstrated significantly higher values in the Lynch syndrome than in the FCCTX tumors." (PMID 28824332, 2017). "Tumors linked to Lynch syndrome and FCCTX showed significant differences, primarily related to frequent expression of CK20 and nuclear β-catenin in FCCTX and relative over-expression of MUC2, MUC5AC and MUC6 in Lynch syndrome." (PMID 28824332, 2017). "Differences were identified for CK20 and nuclear β-catenin, which were significantly more often expressed in FCCTX than in Lynch syndrome (p < 0.001), whereas MUC2, MUC5AC and MUC6 were overexpressed in Lynch syndrome tumors compared with FCCTX tumors (p = 0.001, < 0.01, and < 0.001, respectively)." (PMID 28824332, 2017). "We further found that FCCTX tumors generally mimicked the profile of the non-neoplastic colorectal mucosa, with CK20+, MUC5AC- and MUC6-, which contrasted to the expression pattern in the Lynch syndrome tumors." (PMID 28824332, 2017).
metastasis (1 paper, 2005). The spread or migration of cancer cells from one part of the body (where they first appeared) to another. "Nearby are the MUC2 and MUC6 genes (11p15) that might be related to lymph node metastasis." (PMID 15870709, 2005).
metastatic disease (1 paper, 2023). "In a recent analysis, multiple mucins, including MUC1, MUC2, MUC5AC, and MUC6, were found to differentiate primary BC from metastatic BC, where MUC1 correlated with the low or early grade, MUC5AC with metastatic disease, and MUC6 emerged as an indicator of poor prognosis." (PMID 36980526, 2023).
mucinous ovarian carcinoma (1 paper, 2024). An invasive malignant neoplasm that arises from the ovary and is characterized by the presence of malignant epithelial cells that contain intracytoplasmic mucin and may resemble the epithelial cells of the endocervix or gastrointestinal tract. "Genes such as MUC2, MUC5AC, MUC6, and MUC13, as well as the predominant intracellular presence of mucin, appear to be involved in the development and recurrence of mucinous ovarian carcinoma and can be used to differentiate between primary ovarian and metastatic lesions." (PMID 39598188, 2024).
Mucinous tumours (1 paper, 2023). "Mucinous tumours overexpress MUC2, a secreted gel-forming mucin that is encoded in the MUC2, MUC5AC, MUC5B and MUC6 genes on chromosome 11." (PMID 36982838, 2023).
nasal polyps (1 paper, 2020). "Compared with normal nasal mucosa, the expression of MUC3 and MUC6 in nasal polyps is downregulated, the expression of MUC2 and muc8 in nasal polyps is upregulated, the expression of MUC5AC and MUC5B in CRS is upregulated, and the expression of MUC5AC in nasal polyps far exceeded MUC1 and MUC2." (PMID 32812123, 2020).
oral squamous cell carcinoma (1 paper, 2023). "After adjusting for other co‐variants, we found that carrying a CC genotype at MUC6 rs6597947 led to a lower risk of developing oral squamous cell carcinoma (OSCC) than wild‐type carriers among non‐betel‐quid chewers." (PMID 37581476, 2023).
pancreatitis (1 paper, 2015). Inflammation of the pancreas. "Expression analyses of fibrosis, pancreatitis, or desmoplasia associated markers (α-SMA, Shh, COX-2, Muc6, Col1a1, and Ctgf) were performed by IHC and/or qRT-PCR." (PMID 25803032, 2015).
parasite infection (1 paper, 2022). "We found TFF1-3, MUC1, MUC6, and MUC20 expression in the bovine abomasal organoids reported here, which is consistent with their feasibility as a relevant in vitro culture model for studying host responses to parasite infection." (PMID 35846775, 2022).
prostate tumour (1 paper, 2004). "Using PAC120, a xenograft of a human hormone-dependent prostate tumour, and its hormone-independent variants, we analysed the expression of mucins (MUC1, MUC2, MUC4, MUC5AC, MUC5B, MUC6) by immunohistochemistry or reverse transcriptase (RT)–PCR." (PMID 14760390, 2004). "Overall, MUC2, MUC5B and MUC6 were associated with mucinous morphology, and were expressed in HID prostate tumour variants." (PMID 14760390, 2004).
pterygium (1 paper, 2021). A wedge-shaped fibrovascular lesion arising from the bulbar conjunctiva and extending to the cornea. "In contrast, MUC6 was highly upregulated in pterygium, and moderately so in pinguecula." (PMID 34769520, 2021).
pulmonary artery hypertension (1 paper, 2025). "In addition, missense mutation in MUC6 gene contributes to the development of pulmonary artery hypertension." (PMID 40572705, 2025).
small intestinal carcinoma (1 paper, 2014). "We also previously examined mucin expression in small intestinal carcinoma, and found positive expression rates of MUC1, 51.7%; MUC2, 26.7%; MUC3, 55.0%; MUC4, 51.7%; MUC5AC, 33.3%; MUC6, 10.0%; and MUC16, 8.3% (MUC17 expression was not examined)." (PMID 25551773, 2014).
ulcerative colitis (1 paper, 2024). An inflammatory bowel disease involving the mucosal surface of the large intestine and rectum. "MUC6 expression is associated with colonic neoplasms in ulcerative colitis, suggesting that INFLAREs may have a direct role in colitis-associated CRC29,30." (PMID 39567783, 2024).
viral hepatitis (1 paper, 2020). An acute or chronic inflammation of the liver parenchyma caused by viruses. "MUC6, in particular, has been linked with viral hepatitis in biliary epithelium and has a highly common novel missense variant that can significantly damage the protein function." (PMID 32848883, 2020). "Among the proteins encoded by these genes, ubiquitin carboxyl-terminal hydrolase 6 (USP6) regulates plasma membrane localization of ADP-ribosylation factor 6 (ARF6), while mucin 6, oligomeric mucus/gel-forming (MUC6) is involved in reactive biliary epithelium in viral hepatitis." (PMID 32848883, 2020).
tumor (107 papers, 2004 to 2026). "Conversely, high MUC6 expression was associated with smaller tumor size, female patients, and better prognosis." (PMID 40655139, 2025). "In gastric mucosa, MUC6 has been identified as an oncogenic driver, mutated in around 20% of all cases, and its downregulation associated with tumor progression." (PMID 39755998, 2025). "A positive MUC6 immunostaining would literally exclude such tumor entities from diagnostic considerations." (PMID 37057870, 2023). "These discrepant data are likely due to the use of different antibodies and staining protocols and make it impossible to assess the potential diagnostic significance of MUC6 for the distinction of tumor entities." (PMID 37057870, 2023). "For instance, in a study analyzing 17 gastrointestinal IHC tumor-associated markers, only four markers (MUC6, CK17, CD10, and Villin) were significantly associated with OS in patients with GBC." (PMID 37444550, 2023). "For example, MUC6 alterations have been linked to tumor aggressiveness in cancers of the ovaries, breast, stomach, esophagus, colon, pancreas, and bile ducts." (PMID 37057870, 2023). "The case numbers analyzed in this study were large enough to search for associations between MUC6 staining and features of tumor aggressiveness in six different tumor entities." (PMID 37057870, 2023). "In particular, one novelty variant found that the MUC6 gene (chr11:1018257 A>T) was the most frequent across our cohort, in both the tumour and the margin samples, and was then classified as a high impact, stop-gain mutation." (PMID 37504272, 2023). "We previously reported that decreased αGlcNAc glycosylation of MUC6 was associated with high mitotic activity in tumor cells, indicative of the malignant potential of gastric PGA12." (PMID 38062108, 2023). "One tumor had three MUC6 mutations: c.G5685C, encoding p.M1895I, c.C5618A, encoding p.P1873Q and c.C4526T, encoding p.T1509I." (PMID 35574418, 2022). "To demonstrate that MUC6 mutation have effects on in-vivo tumor formation, we used MUC6 mutant (P1873Q) WiT49 cell and control WiT49 cell to establish subcutaneously xenografted nude mice." (PMID 35574418, 2022). "Taken together, these results suggest that MUC6 mutation promotes in-vivo tumor formation via β-catenin." (PMID 35574418, 2022). "Through whole-genome sequencing of 5 WT patients, we identified novel somatic MUC6 mutations in WT, which inhibits β-catenin expression through autophagy-dependent degradation to further affect tumor behaviors." (PMID 35574418, 2022). "On the other hand, MUC6 was expressed in many UC cases and correlated with the clinical markers associated with neoplasia." (PMID 33807999, 2021). "For example, MUC17, MUC5B and MUC6 gene mutations in tumor region T4A of PtA predict the perturbation of O-glycan biosynthesis and processing, and the GO terms in T4A differ from GO terms in other tumor regions." (PMID 26619400, 2015). "In contrast, the HPV-positive tumor had five mutations in four different mucin genes, including the secreted Muc6, and the transmembrane bound Muc4, Muc12 and Muc16." (PMID 23304554, 2012). "One tumor had two MUC6 mutations: c.A5055C, encoding p.L1685F and c.C4631A, encoding p.T1544K." (PMID 35574418, 2022). "Our results showed that MUC6 tumor expression was associated with a better prognosis in patients with well- to moderately differentiated tumors, whereas CK17 or CD10 tumor expression was associated with worse prognosis in patients with poorly differentiated tumors." (PMID 33494186, 2021). "Immunohistochemically, mucin 5AC (MUC5AC) and MUC6 were expressed in the tumor cytoplasm, classifying it as the gastric type." (PMID 41181742, 2025).
tumor (continued). "Immunohistochemical analysis showed positivity for Mucin 5AC (MUC5AC) and MUC6, classifying the tumor as a gastric-type IPMN." (PMID 41181742, 2025). "In a specific study, MUC6 expression was correlated with tumor invasiveness, lympho-vascular invasion, tumor heterogeneity, and poor prognosis." (PMID 40655139, 2025). "Expression of secreted mucins MUC2, MUC5AC, and MUC6 was detected in the cytoplasm (94%, 59% and 12% of all tumours, respectively)." (PMID 39966658, 2025). "MUC-6, MUC5AC, CAIX, and HNF-1 were immunoreactive, and we discovered germline mutations of MUC-6 and CAIX in tumor tissue." (PMID 40018404, 2025). "The involvement of C3 MUC6+ tumour cells in the MHC molecule‐mediated pathways, pertaining to peptide antigen presentation, assumes paramount significance." (PMID 38894657, 2024). "The present study investigated multiple mutations identified from the selected fragments of MUC6 and MUC16 in the tumour and the surgical margin samples collected from the tonsillar tissue of OPSCC patients." (PMID 37504272, 2023). "SOSTDC1, TLR5, MT1G, and MUC6 were downregulated in locally advanced tumor tissue samples, whereas COL8A1 and THBS2 were upregulated (P<0.05)." (PMID 36969001, 2023). "More than 11 600 samples from 119 different tumor types and subtypes were successfully analyzed for MUC6 expression in our study." (PMID 37057870, 2023). "Abnormal MUC6 expression has also been reported from a variety of cancers, and there is growing evidence for a role in tumor development and progression." (PMID 37057870, 2023). "The broad range of tumor types with MUC6 expression limits the utility of MUC6 immunohistochemistry for the distinction of different tumor types." (PMID 37057870, 2023). "Published work demonstrates that MUC6 can also be expressed in several cancer types and can aid in the distinction of different tumor entities." (PMID 37057870, 2023). "In summary, the results of this study show that MUC6 is expressed in a broad range of different tumor entities." (PMID 37057870, 2023). "Overall, 50 (42%) of 119 tumor categories showed a detectable MUC6 staining of at least one tumor with 33 (28%) tumor categories showing at least in one case a strong positivity." (PMID 37057870, 2023). "This study was designed to provide a comprehensive analysis of MUC6 expression across a broad range of different tumor entities." (PMID 37057870, 2023). "The results showed that tumors from MUC6 mutant WiT49 cell had much larger size compared to control cell, but DN-β-catenin dramatically decreased the tumor size of MUC6 mutant WiT49 cell." (PMID 35574418, 2022). "The results show that MUC6 inhibited tumor aggression via autophagy- dependent β-catenin degradation and MUC6 mutations compromised autophagy- dependent β-catenin degradation as well as the tumor-suppressive effects of MUC6." (PMID 35574418, 2022). "Immunohistochemically, tumor cells show diffuse positivity for MUC6, while MUC2-positive goblet cells or MUC5AC-positive gastric foveolar metaplastic cells are observable, but are usually scattered." (PMID 35204432, 2022). "In our study of tumor recurrence, a significant correlation with RFS was observed in gene mutations (ATR, ERBB3, KDR, and MUC6) and fusions (GOPC-ROS1 and NTRK1-SH2D2A)." (PMID 34599262, 2021). "Our results suggest that tumor MUC6, CK17, and CD10 can be considered as potential prognosis markers for GBC." (PMID 33494186, 2021). "The tumor cells showed mild nuclear atypia and was positive for pepsinogen-I (PG-I) and mucin-6 (MUC6)." (PMID 34032698, 2021).